CD4 (CD4 molecule)
Diseases named in the same sentence as CD4 in open-access papers (continued):
Sharing a sentence is not in itself a finding about the gene and the disease.
infection (continued). "Strong evidence supports that HIV can independently replicate in the CNS during untreated infection and that the virus can establish a latent reservoir in this anatomic compartment, which may be distinct from the one in circulating CD4+ T cells." (PMID 28046096, 2017). "Infection with any LR type (aOR = 41.28; 95%CI = 13.57–125.62), >1 LR type (aOR = 4.14; 95%CI = 1.60–10.69), being <6 months on antiretroviral treatment (aOR = 6.90; 95%CI = 1.63–29.20) and having a CD4+ count <200 cells/μL (aOR = 5.48; 95%CI: 1.60–18.78) were associated with having AGWs." (PMID 28832285, 2017). "Indeed, a longitudinal study of SIV infection in NHP spleen revealed large numbers of HIV-1–infected CD4+ T-cells during acute infection that resulted in T-cell depletion and morphological changes in tissue at later stages of infection, consistent with human autopsy studies." (PMID 28198699, 2017). "This suggests that different subpopulations of antigen-presenting cells in the lung may be available to encounter tissue resident CD4 T cells established from previous infections or facilitate the recruitment of additional virus-specific CD4 T cells from circulation." (PMID 28883436, 2017). "Additionally, CD4M9 inhibited infection of CD4+ cells by different HIV-1 strains." (PMID 28074089, 2017). "Furthermore, infection of CD4+ T cells is limited by p110γ PI3K inhibition." (PMID 28892135, 2017). "Furthermore, as HIV‐specific Tregs are induced during infection, the increase in CD4+ Treg frequencies may be, in part, driven by antigenic stimulation." (PMID 28133804, 2017). "Pioneering reports suggested that DC-SIGN, a C-type lectin expressed on immature DCs that patrol peripheral mucosae in search of invading pathogens, could capture HIV-1 early after viral invasion, travel to lymphoid tissues, and establish productive CD4+ T cell infection via trans-infection." (PMID 29209326, 2017). "The 2016 WHO consolidated guidelines on the use of ARV drugs for treating and preventing HIV infection recommend testing and treating all patients, regardless of CD4 cell count, and the use of pre-exposure prophylaxis (PrEP) for those at high risk of infection." (PMID 28146591, 2017). "Although the function of GRAIL in CD4 T cells has been studied extensively for the development of tolerance, with its participation having been demonstrated in the development of autoimmune diseases, only recently has its role been studied during T cell dysfunction in the course of infections." (PMID 28114324, 2017). "In addition, IL-13-producing ILC2s were shown to cooperate with CD4+ T cells during N. brasiliensis infection to mediate larval killing in the small intestine during primary infection and in the lung following secondary infection." (PMID 29163497, 2017). "It must be noted that this population might represent a steady state CD4+ population presumably after a contraction phase since these were sampled 31 days after the initial LdWTLLO infection (21days of LdWTLLO + 10days after LdCen−/−2W infection)." (PMID 29312315, 2017). "Also, macrophages may be productively infected by mechanisms different from CD4+ T cells such as by phagocytosis of infected cells or by direct spread of infection between monocyte-derived macrophages using nanotubes." (PMID 29259605, 2017). "An increase in CD8+ T cells carrying viral replication complexes in the periphery was associated with a drop in peripheral CD4+ and CD8+ T cells at day 3 post infection, suggesting viral replication in the periphery might affect T cell proliferation and activation." (PMID 28290449, 2017). "Consequently, the lack of IL-13 expression by CD4+ T cells at the site of infection is likely to be causative for the enhanced susceptibility of Egfrfl/flxCd4-cre mice to H. polygyrus infection." (PMID 29045902, 2017).
infection (continued). "Good CD4 T cellpriming by peptide vaccination could improve antibody responsealso during natural infection that could occur in the immunizedindividuals, "primed by vaccines, boosted by natural infection" isa good vaccine strategy." (PMID 28584450, 2017). "Interestingly, infection of NK cells by HHV-6 also leads to de novo expression of CD4, an antigen not expressed by NK cells, thereby predisposing these cells to infection by HIV-1." (PMID 29194419, 2017). "These increased frequencies of CXCR3+ memory CD4 T cells in macaque LN versus reduced frequencies of CXCR3+ memory CD4 T cells in AGM LN during the acute phase of infection may be due to mobilization of these cells in the context of a strong pro-inflammatory context (CXCR3-ligands) in macaques." (PMID 27509048, 2016). "Previous studies showed that anti-Tat IgM and IgG, although present in a small proportion of HIV-infected individuals, are more frequently found in the asymptomatic stage of infection and in non-progressors and are associated with maintenance of CD4+ T cell counts and low viral load." (PMID 27450538, 2016). "Thus, IL-27 production in response to MCMV is dependent upon type-1 IFNR signaling, and this axis acts during the initial days of infection to promote the accumulation of MCMV-specific IL-10+CD4+ T cells, subsequently promoting virus persistence and shedding from the mucosa." (PMID 27926930, 2016). "At later time points, infection proceeded with robust viral replication and evident CD4+ T cell depletion, except in one mouse that showed complete suppression of viral replication (no virus detected anymore at Weeks 3 and 4) and preservation of CD4+ T cell count." (PMID 27128948, 2016). "Thus, both quantitative and qualitative defects in the CD4+ T cell repertoire, as reflected by the profoundly depressed proportions of CD4+ splenocytes from Ctsl-/- mice at baseline and after infection, may result in impairment in early host defenses." (PMID 27716790, 2016). "Levels of CD8+ T-cells and CD19+ B-cells in mice depleted of CD4+ T-cells prior to a secondary infection were similar to those observed in immune-intact animals, suggesting that CD8+ T-cells and CD19+ B-cells may be important for a maximal secondary immune response." (PMID 27242785, 2016). "Considerable evidence suggests that CD4 + CD28null T-cell expansions, predominantly seen in Cytomegalovirus (CMV) seropositive individuals, are associated with systemic dysregulation of immune function leading to a heightened risk of infection and cardiovascular disease." (PMID 27450392, 2016). "Since HIV predominantly infects CD4 T cells, both the availability and the HIV-permissivity of local CD4 T cells may dictate whether or not infection is established, with a limited number of highly susceptible cells driving initial mucosal infection." (PMID 27898732, 2016). "Additionally, CD4 T cells from patients with HIV could be intrinsically altered, as suggested by the limited proportion of HIV-infected patients recovering their pre-infection CD4 T cells counts under virus-controlling antiretroviral therapy." (PMID 27875993, 2016). "However, evoking concomitant CD4+ T cell responses against Env or other HIV-1 proteins such as Gag is also desired as helper CD4+ T cells can produce effector proteins to hinder infection and are essential for driving effective B cell responses, while cytotoxic CD8+ T cells can complement ADCC." (PMID 27077384, 2016). "Based on the differential pattern of in vivo infected CD4+ T cell subsets in SIV-infected SMs vs. SIV-infected rhesus macaques (in which the infection is pathogenic), we had hypothesized that CD4+ TEM and/or CD4+CCR5+ TM of SMs may undergo faster turnover upon SIV infection." (PMID 27227993, 2016).
infection (continued). "In addition, at 5 days post infection, the proportion of activated (CD44high/CD62Llow) CD4+ T and CD8+ T lymphocytes was augmented to 55.5% and 39.9%, when compared with 14.7% and 12.2% in uninfected controls or 27.8% and 10.2% in infected mice treated with E6446, respectively." (PMID 27808089, 2016). "However, administration of high doses of IFNα to SIV-infected African green monkeys, which naturally tolerate infection, does not enhance CD4 T cell loss or pathogenesis." (PMID 27010978, 2016). "The next phase, also calledacute or primary infection phase, 2-4 weeks after infection, is characterized byrelatively high levels of viremia (up to 107 or more copies of viral RNA/mL ofblood) and large fractions of infected CD4+ T cells in blood and lymphnodes." (PMID 28357381, 2016). "The abundance of F4/80+ antigen presenting cells may be critical to the development of CD4+ T cell hypo-responsiveness, particularly as it has been shown that F4/80+ alternatively activated macrophages depress CD4+ cell responses following infection with filarial parasites." (PMID 27505056, 2016). "Therefore, it would be interesting to investigate whether DENV-specific CD4 Trm cells develop following infections and whether CX3CR1 plays a role in their establishment and maintenance in non-lymphoid tissues such as the skin." (PMID 28003809, 2016). "Whereas B-cells and antibodies are clearly dispensable for H. pylori control, it is now clear that CD4+ effector T-cells, and in particular Th1 and Th17-polarized T-effector cell subsets along with their signature cytokines, are critical for proper control of this infection." (PMID 27322319, 2016). "CCR5-dependent recruitment of CD4+Foxp3+ Tregs may dictate the magnitude of the CD4+ Th1 and/or Th17 subset responses to favor a detrimental or beneficial effect on pathogen persistence at the site of infection." (PMID 27439902, 2016). "In addition to classical Th9 cells responding to antigen-stimulation, we also observed increased frequencies of Th2 cells expressing IL-9 (IL-4/IL-9 co-expressing), indicating that other CD4+ T cell subsets also respond to Ss infection with the capacity to produce more IL-9." (PMID 26730582, 2016). "Despite previous studies showing that unstimulated and CCL19-treated resting CD4+ T-cells lack activation markers that are required for productive infection, one important issue we aimed to address in these experiments was whether there was low level productive infection in this model." (PMID 27383184, 2016). "Before encountering CD4-positive cells, the virus binding to these receptors can affect mucosal cells attachment and transport across epithelial layers, tropism and tissue invasion and bring Env into close proximity with CD4, thereby increasing the efficiency of infection." (PMID 27721488, 2016). "However, our results also evidence the long-term stability of viral reservoirs in naïve CD4+ T cells when the infection is driven by CXCR4-tropic viruses, as is the case of Pt-3, in whom TN cells account for >80 % of the total pool of infected cells at all the time points evaluated." (PMID 27484989, 2016). "The failure of the CD4+YFP+GFP+ T cells to express characteristics of memory T cells after malaria infection indicated that the CD4+YFP+GFP+ T cells were lost from the Ag-experienced CD4+ T cell population after infection because they were short-lived and rapidly died postinfection." (PMID 27630165, 2016). "Infection with HIV-1 can result in apoptotic cell death through activation of both death receptor-mediated and Bax/mitochondrial-mediated apoptotic pathways, which cause a progressive depletion of a select group of immune cells namely the CD4+ T helper cells leading to immunodeficiency." (PMID 26848681, 2016).
infection (continued). "We previously demonstrated that acute murine T. cruzi infection results in an impaired peripheral CD4+Foxp3+ T cell differentiation due to the acquisition of an abnormal Th1-like phenotype and altered functional features, negatively impacting on the course of infection." (PMID 26745276, 2016). "Thus, CD38+ CD4+ T cells were associated with a ‘naïve-like’ effector T cell phenotype (CD45RA+Ki67+Bcl2low), and the proportion of cells expressing each marker was significantly affected upon infection within this cell subset." (PMID 27662621, 2016). "CD4+ T-cells impaired function may hinder infection control in the intestinal lumen." (PMID 28070527, 2016). "Although this is yet to be proven, our thought is that one could make the hypothesis that the increased CD4 T cell population observed 12 years following the challenge could be indicative of a high viral load during infection driving a robust T helper response in these individuals." (PMID 27187443, 2016). "Therefore, control of CD4+ T cell activation during HIV-1 primary infection could regulate viral replication, decreasing the size of the reservoir, and reducing the depletion of CD4+ T cells." (PMID 26973648, 2016). "Thus, to identify additional T cell-dependent factors that might regulate myeloid cells during infection, we performed transcriptome analysis on activated CD4+ T cells sorted from infected mice 6 d.p.i., when production of many cytokines peaks." (PMID 27923070, 2016). "Also, the fact that CD4+Foxp3+ Tregs can regulate the progression of WNV encephalitis in an infection model using depletion of CD4+Foxp3+ Treg cells suggests an important role for CD4+Foxp3+ Tregs in regulating the progression of fatal neuroinflammation caused by flaviviruses." (PMID 27439902, 2016). "The patterns detected with protein vaccination recapitulated many of those observed in the context of infection, suggesting that the milieu associated with infection was not a deciding factor in determining the distribution of CD4 T cells between Tfh and NonTfh populations." (PMID 27329272, 2016). "Thus, we speculate that the function of our novel population of CD38+ CD4+ T cells during infection might be to control and restrain the immune response, rather than to promote it." (PMID 27662621, 2016). "To test whether KIR or HLA are associated with differences in the course of disease we used a linear mixed model approach to model post-infection viral loads accounting for differences in times of viral load or CD4+ T-cell count measurement and inter-participant variation amongst 139 women." (PMID 26809736, 2016). "Previous studies have demonstrated that CD4 T cells with cytotoxic potential as assessed by the expression of CD107a are present in patients associated with both primary and secondary DENV infections, although the frequencies of these cells vary according to infection history and disease severity." (PMID 28003809, 2016). "Similarly, parasitized splenic dendritic cells isolated from LdCen-/- infected young and aged BALB/c mice after 4 days of infection displayed up-regulation of many proinflammatory cytokine genes along with generation of enhanced CD4+Th1 response compared to LdWT infected mice." (PMID 27580076, 2016). "In terms of ART, not only the rate of CD4 cell count recovery in peripheral blood after ART initiation is associated with TB IRIS, but the ART may also trigger local immune reconstitution via increased numbers of infiltrating MTB-specific CD4+ T cells at the site of infection." (PMID 27182275, 2016). "In addition, factors that may be associated with misclassification of HIV-1 recent infection of HIV-1 including viral loads and subtypes as well as CD4+ cell counts must be evaluated." (PMID 27802337, 2016).
infection (continued). "We studied HIV-1 integration site patterns in monocyte-derived macrophages (MDMs) and activated CD4+ T cells derived from seven antiretroviral therapy (ART)-treated HIV-1-infected individuals whose cells were infected ex vivo with autologous HIV-1 isolated during the acute phase of infection." (PMID 27067385, 2016). "Immunization with CD4 T cell epitopes derived from DENV NS proteins NS2B and NS3 can accelerate viral clearance following DENV challenge, suggesting that the induction of cytotoxic CD4 T cells by vaccination may be beneficial for the control of secondary infections with DENV." (PMID 28003809, 2016). "Additionally, loss of CD4+ T-cells prior to secondary infection did not significantly affect the number of BMPCs." (PMID 27242785, 2016). "To examine whether the reduced proportions of infiltrating T cells reflected a decrease in antigen-specific T cell responses, we assessed the proportions and numbers of CNS-infiltrating virus-specific CD4+ T cells during the course of infection in the P2/P3-Tg and control mice." (PMID 27250711, 2016). "Thus, the IL-2 elevation during acute infection is not sufficient to block the massive depletion of CD4 T cells caused by the strong cytotoxic effects of the innate immune response and the substantial cytotoxicity due to peak viremia." (PMID 27145859, 2016). "Several lines of evidence support the idea of a cooperative function between antibody and CD4+ T cells and provide evidence that CD4+ T cells are responsible for the recruitment and/or activation of a local effector cell population that functions with antibody to resolve infection." (PMID 27600502, 2016). "The data illustrate that despite the comparable CD4+ T cell recruitment to lungs of WT mice and p55∆NS mice, persistent p55TNFR expression might play a suppressive role in T cell activation during early infection." (PMID 27995986, 2016). "Neurons do not express the CD4+ receptor and thus are not capable of productive infection; therefore, the HIV-associated neurological complications causing neuronal damage mainly result from inflammatory factors and neurotoxic substances released by infected as well as activated, uninfected cells." (PMID 26539167, 2015). "Thus, in acute phase of infection, type I IFN-induced CD169 on inflammatory DCs might support establishment of infection in mucosal CD4+ T cells." (PMID 25760631, 2015). "In our report, we show that breast milk from HIV-1-infected women significantly inhibited infection of primary Ugandan subtype A virus in human intestinal mucosa, presumably in susceptible CD4+ T cells since intestinal macrophages do not support HIV-1 replication, as we have reported." (PMID 26680219, 2015). "Similarly, in a study performed on chimpanzees acutely infected with HCV, the dynamics of viremia and course of infection correlated with intrahepatic accumulation of HCV antigen-specific CD4+ and CD8+ cells and with their response, as measured by interferon production." (PMID 26637466, 2015). "Our results may overestimate the frequency of infection in γδ cells compared to r-CD4 cell calculations, as viral outgrowth starts during the first 24 hours of incubation, when γδ cells can spread the virus to the γδ-CD8-depleted-PBMC, required for Vδ2 cell activation." (PMID 26473478, 2015). "However, the loss of CD4+ T cells as a result of JRCSFNefdd infection was not as great as for JRCSF (p < 0.05 for bone marrow, spleen, lymph node, lung and liver)." (PMID 26169178, 2015). "Interestingly, infecting resting CD4+ T cells with our HIV Duo-Fluo I virus produced a significant amount of silent infection events, in which expression of both fluorescent proteins was silenced, camouflaging latently infected cells within our uninfected population." (PMID 26067822, 2015).